PABPC1 (poly(A) binding protein cytoplasmic 1)
Diseases named in the same sentence as PABPC1 in open-access papers (continued):
Sharing a sentence is not in itself a finding about the gene and the disease.
tumor (49 papers, 2004 to 2025). "Specifically, the expression of PABPC1 in ESCC positively correlates with tumor differentiation, and high PABPC1 expression in ESCC patients is associated with shorter median survival time post-surgery compared to low PABPC1 expression (p = 0.043)." (PMID 39741631, 2024). "Taken together, these data suggest that PABPC1-induced tumor progression is associated with IFI27 expression." (PMID 35346324, 2022). "used their own cohort and public database TCGA sample analysis to conclude that PABPC1 expression is upregulated in esophageal squamous cancer tissues and its elevated expression is associated with tumor cell differentiation and poor prognosis in patients." (PMID 36531055, 2022). "Moreover, PABPC1 is highly expressed in various tumor tissues and is strongly associated with an unfavorable prognosis, particularly in HCC." (PMID 40290127, 2025). "Furthermore, since accumulating studies have shown that the role of epithelial–mesenchymal transition (EMT) in OC is closely linked to the invasion and metastasis of tumor cells, the relationship between PABPC1 and EMT-related markers was also investigated." (PMID 34027108, 2021). "Collectively, these data supported that SLC27A5 deficiency facilitates the expression of PABPC1 and short 3'UTR isoforms of METTL14, thereby inhibiting METTL14 expression and promoting tumor progression." (PMID 40290127, 2025). "Comparison of the Cancer Genome Atlas (TCGA) and Genotype‐Tissue Expression (GTEx) datasets with normal tissues showed notable upregulation of PABPC1 in 31 tumor samples." (PMID 40013670, 2025). "At the different phases of clinicopathological staging, we observed that PABPC1 expression in patients with PAAD with a high TNM stage (stage IV) was marginally enhanced compared with that in the patients with a low tumor stage (stage I, II, and III)." (PMID 37506150, 2023). "The findings confirmed that PABPC1 was abnormally expressed in patients with PAAD, which occurs at an advanced tumor stage and is linked with poor prognosis." (PMID 37506150, 2023). "Numerous studies have shown that PABPC1 affects multiple biological events, such as tumor cell proliferation, apoptosis, and metastasis, which showcases a key role of PABPC1 in the occurrence and development of tumors." (PMID 37506150, 2023). "As an alternative option, the combination of multiple tumor-suppressing proteins such as PABPC1, ENO1, MSN, etc. can be considered a protein-based cocktail therapy." (PMID 36923539, 2023). "The immunohistochemistry score was recorded based on the percentage of PABPC1 expression in the tumor region." (PMID 36803974, 2023). "Evidence from numerous studies has shown that PABPC1 plays a dual role (tumor promoter or antitumor) in tumor initiation and progression and contributes to tumor cell proliferation, apoptosis, and metastasis and tumor recurrence." (PMID 37506150, 2023). "The results indicated that ENO1, MSN, and PABPC1 were double-edged swords, acting as intracellular tumor promoters and extracellular tumor suppressors." (PMID 36923539, 2023). "Most past studies on PABPC1 in tumors have focused on detecting gene copy number and/or protein expression of PABPC1 in different types of tumor tissues or cells, and its high expression in some solid tumors is associated with poorer patient prognosis." (PMID 36531055, 2022). "Studies of PABPC1 initially revealed its broad function as a tumor and metastasis-promoting protein, and PABPC1 gene overexpression was associated with abnormalities in tumor cell proliferation, apoptosis, invasion and distant metastasis." (PMID 36531055, 2022). "the tumor suppressive function of MKRN3 is dependent on its E3 ubiquitin ligase activity, and MKRN3 missense mutations were found to impair MKRN3-mediated PABPC1 ubiquitination in patients." (PMID 36531055, 2022).
tumor (continued). "The expression of PABPC1 in 31 tumor specimens was analyzed using the Tumor Genome Atlas (TCGA) and Tissue Genotype Expression (GTEx) datasets in comparison to normal tissues." (PMID 36531055, 2022). "Elevated PABPC1 expression was correlated with tumor cell differentiation and poor prognosis in patients." (PMID 35346324, 2022). "Further study of the relationship between PABPC1 and other tumors is important for understanding the mechanisms by which PABPC1 promotes tumor development and its potential role in tumor therapy." (PMID 36531055, 2022). "In this paper, we review the abnormal expression, functional role, and molecular mechanism of PABPC1 in tumorigenesis and provide directions for further understanding the regulatory role of PABPC1 in tumor cells." (PMID 36531055, 2022). "Nude mice were subcutaneously injected with KYSE150 cells stably overexpressing PABPC1, and tumor growth was larger compared with control cells." (PMID 35346324, 2022). "Another research group reported that SNHG14 contributed to tumor cell malignant cells by increasing poly(A) binding protein cytoplasmic 1 (PABPC1) expression through H3K27 acetylation." (PMID 34631721, 2021). "We observed that silencing of SNHG14 induced a remarkable reduction in tumor size, while overexpression of PABPC1 impaired the suppression of SNHG14 knockdown on tumor growth." (PMID 32811821, 2020). "In the in vivo study, PABPC1 overexpression combined with BDNF-AS overexpression produced the smallest tumor and the longest survival." (PMID 32015336, 2020). "Thus, the upregulation of PABPC1 may be one underlying reason for tumor formation." (PMID 30863671, 2019). "Our investigation also identified PABPC1 as an HSP70 client protein present in mitochondria of tumor cells." (PMID 28484090, 2017). "The expression of PABPC1 was localized inside the cytoplasm of tumor cells." (PMID 36803974, 2023). "The results of this study indicate that PABPC1 may function as a tumor promoter in PAAD, accelerating BXPC3 cell proliferation and metastasis by regulating COL12A1 expression." (PMID 37506150, 2023). "Dysregulation of PABPC1 expression is observed within multiple tumor types." (PMID 36803974, 2023). "The expression pattern of PABPC1 in NPC was similar to that in ESCC could be due to the squamous derivation of tumor cells." (PMID 36803974, 2023). "Besides ENO1 and MSN, the engineered CM was enriched with polyadenylate-binding protein 1 (PABPC1) which also showed an opposing tumor-regulating role inside and outside tumor cells." (PMID 36923539, 2023). "We found that the IFI27 immunohistochemistry score was positively correlated with PABPC1, with approximately 78.3% of tumor tissues (83/106) with high IFI27 expression showing high PABPC1 staining, and 59.5% (50/84) of those with low IFI27 expression displaying low PABPC1 staining." (PMID 35346324, 2022). "Taken together, our results demonstrate that PABPC1 plays a tumor promoter role in ESCC and may therefore be a therapeutic target for treating ESCC." (PMID 35346324, 2022). "PABPC1 is involved in a variety of signaling pathways involved in tumorigenesis and progression, including Nfr2 signaling, Hippo signaling and PTEN signaling, and PABPC1 may be a potential target for tumor therapy." (PMID 36531055, 2022). "In addition, PABPC1 overexpression combined with BDNF-AS overexpression led to the smallest tumor among all groups." (PMID 32015336, 2020).
tumor (continued). "PABPC1 was corrected with tumor progression and patient's prognosis in esophageal cancer." (PMID 32015336, 2020). "These in vivo data imply that SNHG14/PABPC1 promotes tumor progression via PTEN signaling in vivo." (PMID 32811821, 2020). "Additionally, analysis of the MSKCC cBioPortal for Cancer Genomics database showed that PABPC1 was up-regulated in 44 of 216 (20%) tumor samples." (PMID 26176602, 2015). "We further investigated whether PABPC1 could promote tumor angiogenesis through exosomes." (PMID 35346324, 2022). "We further investigated whether PABPC1 could promote tumor angiogenesis." (PMID 35346324, 2022). "However, low expression of PABPC1 could promote tumor cells growth and lead to a poor prognosis in esophageal cancer." (PMID 34027108, 2021). "After PPI hub genes and module analysis as well as miRNA target gene prediction, our present study preliminarily suggests downregulated ATP5H, SOD1 and upregulated EIF4G2, PABPC1 may be especially important genes involved in amorphous SiNPs-mediated tumor initiation." (PMID 30863671, 2019). "In addition, immunohistochemistry (IHC) analysis was conducted to determine whether SNHG14 affects the expression of PABPC1 in xenograft tumour tissues." (PMID 30063126, 2018). "Through co‐immunoprecipitation and mass spectrometry experiments, we found that circFOXK2 interacts with PABPC1, and the circFOXK2/PABPC1 complex maintains the stability of STMN1 mRNA, promoting the process of tumor epithelial–mesenchymal transition (EMT)." (PMID 40013670, 2025). "This study revealed the unconventional use of tumorigenic factors such as PABPC1, ENO1, and MSN as extracellular tumor-suppressing proteins, which were enriched in AMPK-inhibited PBMC/lymphocyte-derived CM." (PMID 36923539, 2023). "Western blotting and qPCR results indicated that HOXD9, PABPC1, and PAK1 were usually upregulated, whereas PAXIP1-AS1 was frequently downregulated in the 15 tumour samples examined compared to that in the paired paracancerous tissues from the same patient." (PMID 37225681, 2023). "LncRNA SNHG14 upregulates PABPC1 through H3K27 acetylation and regulates PTEN signaling in hepatocarcinogenesis to promote tumor cell proliferation and angiogenesis." (PMID 36531055, 2022). "sh-SNHG14/PABPC1 effects on cell proliferation and angiogenesis was regulated by inhibition of PTEN signaling, a tumor suppressor involved in cell proliferation or angiogenesis through negative regulation of PI3K/Akt signaling or VEGF expression, respectively." (PMID 36531055, 2022). "To analyze the mechanisms of regulated exosomes in controlling tumor angiogenesis, we performed RNA-seq to identify DEG profile and signaling pathways in HUVECs incubated with exosomes derived from PABPC1-overexpressing or control KYSE150 cells." (PMID 35346324, 2022). "According to the IHC scores, PABPC1 expression in ESCC tissue was positively and significantly correlated with tumor differentiation." (PMID 35346324, 2022). "Taken together; these data suggest that PABPC1 increases ESCC cell proliferation, invasion, and migration in vitro, and tumor formation in vivo." (PMID 35346324, 2022). "Mechanistically, leukemic cells secrete miR-19a-3p into the tumor microenvironment via small extracellular vesicles (sEVs), which are controlled by the NPM1 mutant protein/CTCF/PABPC1 signaling axis." (PMID 36531055, 2022). "To further evaluate the effects of PABPC1 and IFI27 on tumor growth, we established xenograft mouse models of ESCC (6 mice per group)." (PMID 35346324, 2022).
tumor (continued). "Furthermore, the combination drug decreased the mRNA expression levels of downstream c-Myc targets, including CDK4, PABPC1, ATF4, BCL2L12, and HMGA 31, in MDA-MB-231 and BT-549 cells, which are important effectors of c-Myc inhibition-induced tumor suppression." (PMID 41281757, 2025). "In addition, polyadenylation binding protein 1 (PABPC1) interacts with PLC-β1 can further enhance the EMT process mediated by PI3K-AKT pathway, which is an important mechanism of early metastasis of tumor cells." (PMID 37576896, 2023). "However, the average percentage of staining tumor cells in NPC was lower than in ESCC, leading to a lower cut-off value of PABPC1 expression in NPC." (PMID 36803974, 2023). "However, the patients had significantly shorter OS and DFS time at an advanced stage (III + IV) (both p < 0.001), depicting a correlation between PABPC1 upregulation and NPC tumor progression." (PMID 36803974, 2023). "PABPC1 interacts with lncRNA-PAGBC in gallbladder cancer, enhancing the stability of the latter, while lncRNA-PAGBC competitively binds miR-133b and miR-511 and activates the AKT/mTOR pathway to promote tumor growth and metastasis." (PMID 36531055, 2022). "Furthermore, we found that PABPC1 promotes ESCC cell proliferation, migration, and invasion, and inhibits apoptosis, indicating that PABPC1 acts as a tumor promoter in ESCC cells." (PMID 35346324, 2022). "The focal adhesion structures were, in most cases, hardly identifiable in clinical specimens; however, close observations of immunofluorescent staining validated the co-localizations of FAK and five protein antigens (GRB7, FLNA, HSP90, PABPC1, and EZR) in these clinical tumor tissues." (PMID 33067514, 2020). "Our result suggests that PABPC1 could also participate and potentiates this process, allowing IBC cells to adapt to the persistent hypoxia they experience as tumor emboli." (PMID 21339811, 2011). "Given the critical role of PABPC1 in mRNA stability, we aimed to investigate whether circFOXK2 promotes mRNA stability by interacting with PABPC1, thereby affecting STMN1 expression and driving tumor progression." (PMID 40013670, 2025). "In addition, PKP3 could closely bind to RNA-binding proteins such as FXR1 and PABPC1, indicating that PKP1/2/3 can participate in cell connection and tumor progression through its interacting proteins." (PMID 33088217, 2020). "In addition, PABPC1 transcript up-regulation in EOC tumor samples compared with nonmalignant control tissues and in EOC patients with short OS was found by an in silico analysis of publicly accessible databases, suggesting its potential value as a prognostic biomarker." (PMID 36229065, 2022). "The expression levels of FCGBP, PABPC1 and NDRG1 were higher and the expression levels of ADH1A, CYP3A4 and ADH1B were lower in tumour tissues than in adjacent nontumour tissues." (PMID 35109839, 2022).
infection (46 papers, 2011 to 2026). The state of being infected such as from the introduction of a foreign agent such as serum, vaccine, antigenic substance or organism. "Further immunofluorescence analysis revealed that rH234A infection resulted in approximately threefold more cells exhibiting PABPC1 nuclear accumulation—a hallmark of RNase L activation—supporting the idea that Nsp15/EndoU antagonizes this pathway." (PMID 40838727, 2025). "Compared to PR8 infection, A/Cal/7 infection caused even higher fraction of infected cells with nuclear PABPC1." (PMID 38629840, 2024). "Despite some small differences between cell lines, we found a strong correlation between half-life changes observed during infection of Calu-3 cells and those observed upon PABPC1 and PABPC4 knockdown in HeLa cells (Rs = 0.51)." (PMID 41279592, 2025). "Consistent with the SARS-CoV-2 findings, we found that changes in mRNA abundance observed upon MHV infection strongly correlated with those observed upon PABPC1 depletion (Rs = 0.57)." (PMID 41279592, 2025). "To further validate that PABPC limitation during infection contributes to host mRNA degradation, we temporally increased PABPC1 levels during infection by stabilizing a PABPC1 construct containing the destabilizing degron ecDHFR66." (PMID 41279592, 2025). "First, we infected A549-ΔMAVS cells with the A/California/7/2009(H1N1) strain of influenza A virus (A/Cal/7) and visualized the distribution of PABPC1 and poly(A) RNA using ImmunoFISH at 20 h post-infection (hpi)." (PMID 38629840, 2024). "One of these proteins, PABPC1, is a poly(A) binding protein that shuttles into the nucleus during infection." (PMID 37068108, 2023). "We analyzed PABPC1 localization via immunofluorescence in WT and RL-KO A549 cells following infection with either dengue virus serotype 2 (DENV2) or SARS-CoV-2 (using A549ACE2 cells), both of which activate RNase L." (PMID 36318584, 2022). "Here, we found that the infection of PEDV downregulated the expression of poly(A)-binding protein cytoplasmic 1 (PABPC1) at the later infection stage in Vero cells." (PMID 35746667, 2022). "In this study, we identified that PABPC1 protein expression upregulated in the early stage and downregulated at the later infection stage of PEDV infection in Vero cells." (PMID 35746667, 2022). "By contrast, PABPC1 remained cytoplasmic in HSV1 vhs-GFP infected cells even as late as 20 h after infection." (PMID 35758691, 2022). "Viral RNA, VP1 protein, and host PABPC1 protein levels were compared at the indicated time points (0, 6, and 12 h) after infection." (PMID 32512928, 2020). "After that, SVV induces the cleavage of PABPC1 to promote viral replication, resulting in severe infection and specific clinical symptoms, which provides a novel pathogenesis mediated by SVV." (PMID 32512928, 2020). "In particular, we found that PABPC1, an RBP whose encoding mRNA harbors a TOP-motif, is induced during infection in an mTOR-dependent fashion." (PMID 32479529, 2020). "For example, both the rotavirus protein NSP3 and the rubella virus capsid protein bind to PABPC1 to remove it from the translation initiation complex and relocate it to the nucleus during infection, leading to an inhibition of cellular mRNA translation." (PMID 31649314, 2019). "PAN binds host poly (A)-binding protein C1 (PABPC1) after PABPC1 is translocated to the nucleus during the lytic phase of infection and is required for the late KSHV gene expression, such as vIL-6 and k8.1." (PMID 28603696, 2017). "Our data on PABPC1 expression in fish host shows that mRNA translation is affected during the infection of T. bryosalmonae, thus impacting cellular metabolic activities in the kidney tissue of the host." (PMID 25563603, 2015). "It has been shown that PAN RNA is polyadenylated and binds to poly(A)-binding protein C1 (PABPC1) after PABPC1 is relocalized to the nucleus during lytic infection." (PMID 25375885, 2014).